CTLA4 (cytotoxic T-lymphocyte associated protein 4)
Diseases named in the same sentence as CTLA4 in open-access papers (continued):
Sharing a sentence is not in itself a finding about the gene and the disease.
tumor (continued). "Immunosuppressive cells within the tumor microenvironment disrupt T cell activation and proliferation by increasing the expression of immunosuppressive receptors such as PD-1 and CTLA-4 and by releasing immunosuppressive cytokines like IL-6, IL-10, TGFβ, and VEGF." (PMID 40625850, 2025). "By tumor weight analysis at day 25, significant inhibition could be detected in comparison with the rAd.sT.GM + anti-CTLA-4 treatment to the untreated, rAd.sT.GM, anti-PD-1, and anti-CTLA-4, respectively." (PMID 40104170, 2025). "Additionally, the presence of soluble CTLA-4 (sCTLA-4) in the tumor microenvironment suppresses effector T-cell activation, allowing for tumor evasion." (PMID 41141615, 2025). "The study also demonstrated that anti-CTLA-4 therapy could enhance the ability of cytotoxic T cells to eliminate neoplastic monocytes and granulocytes in coculture systems, suggesting that CTLA-4 blockade may augment immune responses against tumor cells." (PMID 41268532, 2025). "These monoclonal antibodies (mAbs) specifically target inhibitory proteins, including cytotoxic T-lymphocyte antigen-4 (CTLA-4), programmed cell death protein-1 (PD-1), and programmed death-ligand 1 (PD-L1), thereby augmenting T-cell activation and anti-tumor immunity." (PMID 41239350, 2025). "The immune checkpoints CTLA-4 and PD-1/PD-L1 axis are currently central targets of cancer immunotherapy, where checkpoint inhibitors have revolutionized treatment by enhancing anti-tumor T-cell responses." (PMID 40943153, 2025). "This successful conversion therapy reflects the potential additive or synergistic effects of the treatment regimen: CTLA-4 inhibition expanded the tumor-specific T cell clonotype repertoire and PD-1 blockade maintained the cytotoxic activity of effector T cells." (PMID 41211417, 2025). "In this study, we found that LTX-315 significantly decreased the Tregs infiltration, significantly down-regulated the PD-1 expression, and significantly up-regulated CTLA-4 expression in residual tumors, which enhanced the tumor response to anti-CTLA-4 antibody treatment." (PMID 40222972, 2025). "The CTLA-4 inhibitor ipilimumab has shown anti-tumor activity in some patients with DLBCL." (PMID 40862794, 2025). "In brain metastases treated with immunotherapy, initial observations were made in melanoma patients receiving an anti-CTLA-4 antibody, where some individuals showed early enlargement of tumor lesions, followed by a decrease or stabilization of tumor burden in later evaluations." (PMID 41258375, 2025). "By preparing tumor cell suspensions via collagenase digestion of excised tumors, we found that the combination of SFN and anti-CTLA-4 resulted in a more pronounced upregulation of CD8+ CTL population within tumor-infiltrating lymphocytes (TILs) compared to monotherapy." (PMID 39961271, 2025). "In contrast with the notion of inducing anti-tumour activity, initial anti-CTLA-4 blockade data were ambiguous with evidence that anti-CTLA-4 mAbs enhanced mixed lymphocyte responses but also suppressed effector T cells activated by agonist anti-CD3 and CD28 mAbs." (PMID 40265076, 2025). "These regimens aim to remodel the tumor microenvironment—enhancing antigen presentation, elevating T-cell infiltration, and up-regulating checkpoint ligands—thereby augmenting the response to PD-1/PD-L1 or CTLA-4 inhibitors." (PMID 41415276, 2025). "CTLA4 showed mostly weak expression in tumor cells in 45% (17/38) of cases." (PMID 39592485, 2025). "Similarly, tumor size on Day 49 in the NLRP3/α-PD-1 + α-CTLA-4 group was significantly smaller compared to the NLRP3 agonist alone or the ICIs alone group (p = 0.009 and 0.029, respectively)." (PMID 39871312, 2025).
tumor (continued). "The results of our study showed that LTX-315 plus anti-CTLA-4 antibody yielded a favorable anti-tumor effect for residual tumors, which could help lower the tumor recurrence after iRFA of HCC." (PMID 40222972, 2025). "In B16 melanoma and KPC pancreatic cancer mouse models, the addition of an anti-CD93 antibody enhanced the anti-tumor effects mediated by immune checkpoint blockers, such as PD-1 and CTLA-4 monoclonal antibodies, inhibiting tumor growth and prolonging mouse survival." (PMID 40943530, 2025). "Immune checkpoint inhibitors targeting CTLA-4 and PD-1/PD-L1 have achieved durable remissions in select cancers, yet most patients exhibit resistance due to tumor heterogeneity, immunometabolic rewiring, and the immunosuppressive tumor microenvironment." (PMID 40950404, 2025). "Heterogeneity could be attributed to methodological differences in study design, therapeutic regimens (anti-CTLA-4, anti-PD-1/PD-L1, or combination therapy), and tumor microenvironment characteristics across tumor types." (PMID 41278277, 2025). "However, the treatment of single CTLA-4 inhibitors has shortcomings and challenges in tumor heterogeneity, tumor drug resistance, and tumor recurrence." (PMID 40821119, 2025). "Our findings suggest that Fc-optimized anti-CTLA-4 antibodies could be used to reprogram tumor vasculature in poorly immunogenic cold tumors and improve the efficacy of ICT." (PMID 40460830, 2025). "Interestingly, the results showed that the chemo > STING/α-PD-1 + α-CTLA-4 treatment had significantly better tumor growth suppression than chemo > NLRP3/α-PD-1 + α-CTLA-4." (PMID 39871312, 2025). "These therapeutic agents block immune-inhibitory receptors, such as cytotoxic T-lymphocyte-associated protein 4 (CTLA-4) and programmed cell death protein (PD-1) on activated T cells to promote host immunity against tumor cells and improve T cell functionality." (PMID 40872475, 2025). "However, this approach has only been tested in murine models using CTLA-4 and PD-L1 in combination with mechanical high-intensity focal ultrasound, which resulted in complete regression of the contralateral tumour after treatment of the primary tumour." (PMID 40142250, 2025). "By targeting cytotoxic T-lymphocyte antigen 4 (CTLA-4) on T cells, programmed cell death protein 1 (PD-1), and programmed death-ligand 1 (PD-L1) on tumor cells, this approach disrupts immunosuppressive signaling pathways and restores T-cell-mediated antitumor activity." (PMID 41463331, 2025). "Overall, these latter studies hint at two separate mechanisms of anti-CTLA-4-mediated anti-tumour immunity, the first dependent on TREG depletion, but the second more akin to the concept of ‘releasing the brakes’ in which simple blockade is capable of generating productive immunity." (PMID 40265076, 2025). "Targeting immune checkpoints and immune-infiltrating cells within the TIME can enhance anti-tumor immune responses and improve the efficacy of ICIs, with combination therapies such as PD-1/CTLA-4 dual blockade emerging as a principal strategy to enhance the therapeutic outcomes of ICI." (PMID 41153357, 2025). "The combination of PD-1 and CTLA-4 blocks the invasion of increased effector T cells (Teff), resulting in an increased ratio of Teff to regulatory T cells, which is highly beneficial to the tumor." (PMID 39958358, 2025). "Tregs suppress effector T cell activity through various mechanisms, including the secretion of immunosuppressive cytokines (e.g., IL-10 and TGF-β) and the expression of immune checkpoint proteins (e.g., CTLA-4 and PD-1), thereby allowing tumor cells to evade immune surveillance." (PMID 41020815, 2025). "Monoclonal antibodies that block immune checkpoint receptors, such as cytotoxic T-lymphocyte antigen (CTLA)-4, programmed death (PD)-1, and its ligand PD-L1, have shown broad-spectrum activity against a wide range of tumor types, leading to prolonged survival in many patients." (PMID 40641936, 2025).
tumor (continued). "Tumor-intrinsic mechanisms involve loss of antigen presentation (HLA class I loss via immunoediting), JAK/IFNGR1 mutations impairing interferon signaling, and upregulation of LAG3/TIM-3/CTLA-4 checkpoints." (PMID 41007256, 2025). "In addition, flow cytometric analysis showed increased infiltration of CD8+ T cells into the tumor microenvironment after treatment with either the MUC1 mRNA vaccine or CTLA-4 siRNA-loaded NLE, with the combination therapy showing the strongest effect." (PMID 40943370, 2025). "However, despite enhancing T cell activation, targeting CTLA-4 or PD-1 alone is insufficient to fully control tumor progression." (PMID 40698086, 2025). "CTLA-4 inhibition further enhances these effects by reducing regulatory T-cell–mediated suppression and supporting the expansion of activated effector cells within the tumor microenvironment." (PMID 41293268, 2025). "Additionally, a CTLA-4 blockade can deplete immunosuppressive Tregs, further amplifying the anti-tumor response." (PMID 39857692, 2025). "Approximately 10% of patients with advanced gastric cancer treated with anti-PD-1 antibodies experienced rapid disease progression, known as hyperprogressive disease (HPD), wherein PD-1-PD-L1 pathway blockade activated and expanded tumor-infiltrating PD-1+CTLA-4+ Tregs." (PMID 39325360, 2025). "Blocking CTLA‐4 by CTLA‐4 inhibitors such as ipilimumab and tremelimumab may potentially enhance the anti‐tumor activity of T cells." (PMID 40060757, 2025). "We previously demonstrated that RMC exhibits a “hot” immune-inflamed phenotype characterized by upregulation of immune checkpoints such as cytotoxic T-lymphocyte-associated protein 4 (CTLA-4) and programmed cell death protein 1 (PD-1) in the tumor immune microenvironment." (PMID 41290625, 2025). "Targeting TNFRSF4 and CTLA-4 pathways could arouse effective T cells to drive a robust anti-tumor response." (PMID 40535819, 2025). "The role of this factor in GBM remains underexplored; however, it may contribute to the immunosuppressive tumor microenvironment and potentially enhance the effects of PD-1 or CTLA-4 blockade." (PMID 40514725, 2025). "Combining VSV with immune checkpoint inhibitors (such as anti-PD-1/PD-L1 or anti-CTLA-4 antibodies) may further alleviate immune suppression in the tumor microenvironment and enhance the activity of effector T cells." (PMID 40873562, 2025). "Moreover, anti-PD-1 or anti-CTLA-4 monotherapy can improve tumor control and delay tumor progression in CD39-knockout mice." (PMID 40390144, 2025). "In general, the presence of B cells and tumor-associated TLS correlates with a better prognosis in multiple cancer types including CRC [24,], and predicts responsiveness to immune checkpoint inhibitors such as anti-PD1 or anti-CTLA4." (PMID 40602034, 2025). "The tumor‐specific DC/tumor‐fusion cell (FC)/mRNA vaccine in combination anti‐PD‐1/PD‐L1/CTLA‐4 Nbs (PD‐1 Nb20, 99mTc‐Nbs C3, Nb36) could improve the activation, proliferation, cytokine secretion, and tumor cell cytotoxicity of CD8+ T‐cells." (PMID 40536197, 2025). "From their first introduction in 2011, this approach, in which antibodies are used to block key inhibitory receptor checkpoints CTLA-4, PD-1 on T cells, and PD-L1 on tumour cells, has led them to be used as first-line treatments for several cancers, with more clinical trials in progress." (PMID 40265076, 2025). "Additionally, a significant relationship between CTLA-4 expression and tumor grade, particularly in moderately differentiated tumors (G2), was identified (p = 0.000)." (PMID 40861696, 2025). "Furthermore, the expression of molecules such as CD8, CD3, FOXP3, PD1, CTLA4, and GZMB is significantly increased in BRCA1 mutated tumor samples, signifying a robust T cell response in BRCA1 mutant TNBCs but a more prominent T cell exhaustion." (PMID 40830526, 2025). "CTLA-4 inhibition expands the repertoire of T cells capable of recognizing diverse tumor antigens." (PMID 40075753, 2025).
tumor (continued). "The positive associations between CD8+/CTLA-4+ and outcomes, including TTP and DSS in ESC patients, may reflect a tumor microenvironment in which antitumor immunity properties dominate." (PMID 39751903, 2025). "Beyond enhancing CD8+ T-cell infiltration, CTLA-4 silencing may influence additional immunoregulatory mechanisms within the tumor microenvironment (TME)." (PMID 40943370, 2025). "Extending such expression analyses to other tumor types could help identify dog populations most likely to benefit from anti-CTLA-4 therapy." (PMID 40463388, 2025). "Treg, exhaustion and CTLA4/CD38 cGEPs were upregulated in all six tumor types tested (P < 0.05)." (PMID 40903640, 2025). "Although previous investigations have identified expression of PD-1 and CTLA-4 in EOC tumours by immunochemistry staining, our proteomics analysis did not detect PD-1 and CTLA-4 expression, indicating their potentially extremely low levels of expression in these samples." (PMID 39548315, 2025). "These drugs function by blocking inhibitory receptors such as cytotoxic T-lymphocyte antigen 4 (CTLA-4) and programmed cell death protein 1 (PD-1), thereby enhancing the proliferation and cytotoxicity of tumor-infiltrating lymphocytes (TILs) and restoring antitumor immune activity." (PMID 41228247, 2025). "This implies that moderately differentiated tumors may exhibit high levels of CTLA-4 communication, which could reflect tumor immune evasion pathways that are active at these levels." (PMID 40861696, 2025). "Ipilimumab is a CTLA4 inhibitor that can restore and induce T cell-mediated tumor cell killing." (PMID 41001032, 2025). "Notably, combination therapy targeting B7x alongside PD-1/PD-L1 or CTLA-4 blockade reduced tumor burden and overcame resistance to monotherapy." (PMID 42004225, 2025). "In addition to PTT, AuNPs have been used in testing as precise delivery systems for immune checkpoint inhibitors, including anti-PD-1 and anti-CTLA-4 antibodies, which enhance tumor selectivity and lower systemic toxicity." (PMID 40872479, 2025). "As intratumorally administered oncolytic Ads primarily exert their therapeutic effect in the tumor tissues, the overlapping site of T cell activation by αPD-1 could be more beneficial than systemic immune activation by CTLA-4 in controlling primary tumors." (PMID 40335925, 2025). "The authors stated that the enhancement of anti-tumor action of CTLA-4 antibody by Bifidobacterium." (PMID 41237260, 2025). "Such structural and functional versatility translates into therapeutic potential, as BTLA blockade could complement existing checkpoint inhibitors and restore anti-tumor immunity in cancers resistant to PD-1 or CTLA-4 targeting therapies." (PMID 41471273, 2025). "Moreover, the combination of CAN-2409 + prodrug and anti–CTLA-4 antibody treatment further improved control of tumor growth, in part by the enhanced CD8+ T-cell–mediated effector function and diminished regulatory T cell–mediated immunosuppression." (PMID 39881590, 2025). "Modulating CTLA-4 phosphorylation could restore T cell activity and enhance the immune response against tumor cells." (PMID 40040703, 2025). "In fact, tumor size was significantly reduced in 3 out of 8 mice treated with anti-CTLA-4 alone, with complete tumor eradication in two of them, whereas tumor size was reduced in all the mice receiving the combined treatment, with complete eradication in 7 out of 8 of them." (PMID 40918456, 2025). "Recently, a water extract from sporoderm-breaking spores of Ganoderma lucidum (ESG) (oral administration, 400 mg/kg) was shown to downregulate the immune checkpoint molecules PD-1 and CTLA-4, thus restoring T cell functionality and enhancing tumor immune surveillance in tumor-bearing mice." (PMID 40733125, 2025). "Targeting BTLA may restore effector immune cell function, reprogram the tumor microenvironment, and enhance anti-tumor responses, particularly when combined with other immune checkpoint inhibitors such as PD-1 or CTLA-4." (PMID 41471273, 2025).
tumor (continued). "Additionally, CTLA-4 loss can enhance CAR-T cell proliferation and improve their anti-tumor efficacy." (PMID 40260303, 2025). "This may result in immunomodulation, whereas anti–CTLA-4 and anti PD-1 antibodies enhance immune responses to released and circulating tumor antigens with activation of tumor-reactive immune cells." (PMID 40192993, 2025). "Therefore, immune checkpoint inhibitors (ICIs) targeting these three (PD-1, PD-L1, or CTLA-4) have successfully translated to clinical use to induce a robust T cell response to the tumor." (PMID 41180369, 2025). "Overall, the expression of PD-L1 and CTLA-4 by tumor cells in CRC may collaborate to enhance tumor progression, resulting in poorer patient outcomes." (PMID 40149674, 2025). "Mice with orthotopic syngenetic PDAC tumors who received RFA in combination with gemcitabine, anti-PD-1, and anti-CTLA-4 were found to have increased tumor antigen presentation and T cell recruitment and activation as demonstrated by whole RNA-sequencing and spatial transcriptomics." (PMID 40227779, 2025). "Research into anti-CTLA-4 antibodies has shown promising results in improving immune responses in cancer treatments, including BC, by overcoming immune suppression and promoting stronger anti-tumor immunity." (PMID 40693234, 2025). "Similarly, ATLL tumor cells often upregulate immune checkpoint molecules, including PD-1, PD-L1, and CTLA-4, inhibiting T cell function and promoting immune evasion." (PMID 41295262, 2025). "In this study, we combined programmed death-1 (PD-1)/ programmed death ligand-1 (PD-L1) and cytotoxic T Lymphocyte antigen 4 (CTLA-4) inhibitors with a reduced dosage but via an intra-tumor drug delivery strategy to treat recurrent/refractory (R/R) advanced solid tumors." (PMID 41459523, 2025). "SLC13A3 inhibition enhances anti-CTLA-4 efficacy and prolongs survival in mouse tumor models." (PMID 40931345, 2025). "CTLA-4 inhibitors (ipilimumab and tremelimumab) act during T-cell priming, while PD-1 inhibitors (cemiplimab, nivolumab, and pembrolizumab) counter tumor-mediated suppression." (PMID 40940902, 2025). "Several murine studies suggest that CTLA-4 inhibitors may reduce Treg-mediated suppression and eliminate Tregs in the tumor microenvironment (TME) through antibody-dependent cell-mediated cytotoxicity (ADCC)." (PMID 39852828, 2025). "The immunotherapy regimen, comprising a CD40 agonist, CTLA-4, and PD-1 checkpoint blocking antibodies, was applied to assess its impact on tumor growth on the irradiated and a contralateral unirradiated tumor." (PMID 40475579, 2025). "RT and anti-PD-L1 antibody or CTanti-CTLA-4 (9H10 monoclonal antibody) administration in mice reduced TNBC tumor growth and lung metastasis in animals, indicating that RT with blockade of PD-1 or CTLA-4 may be the effective strategy against TNBC metastasis." (PMID 40141437, 2025). "CTLA-4 is composed of 223 amino acids and is upregulated in tumor-targeting T cells." (PMID 40677703, 2025). "As a result of these improvements, the therapeutic efficacy of both Doxil nanomedicine and ICI cocktail (anti-PD-1 and anti-CTLA-4) was significantly elevated, highlighting the potential of this combined approach to optimize treatment outcomes in a tumor setting." (PMID 40837706, 2025). "Mechanistically, Tregs express inhibitory molecules, including cytotoxic T-lymphocyte-associated protein 4 (CTLA-4), inducible T-cell costimulator (ICOS), glucocorticoid-induced TNFR-related protein (GITR), and OX40, both in tumors and tumor-draining lymph nodes." (PMID 41584838, 2025). "Monoclonal antibodies that block CTLA-4 induce tumor regression." (PMID 40861696, 2025). "CTLA-4 blockade enhances early-stage T cell priming and proliferation in lymphoid tissues, whereas PD-1/PD-L1 inhibition reinvigorates exhausted T cells within the tumor microenvironment." (PMID 41013723, 2025).